MITF (melanocyte inducing transcription factor)
Diseases named in the same sentence as MITF in open-access papers (continued):
Sharing a sentence is not in itself a finding about the gene and the disease.
melanoma (continued). "Interestingly, by interrogating TCGA data we have unveiled a negative Pearson correlation between the expression levels of miR-204-5p/miR-199b-5p and MITF in melanoma." (PMID 36418472, 2023). "On the other hand, melanocyte-inducing transcription factor (MITF) was found embedded in long terminal repeats (LTR-Hs) elements, affecting proliferative melanoma, in which any impairments in MITF could deteriorate expression of HERV-K." (PMID 37112663, 2023). "Among them, many of these genes have been confirmed to be closely related to melanoma, such as the reduction of MITF level promoting melanoma invasion, tumor regression being abrogated by silencing CCL5 and CST7 being significantly up-regulated in melanoma patients who respond to ICB treatment." (PMID 38008419, 2023). "Indeed, both melanogenesis and invasive capabilities depend on MITF levels and activation in melanoma." (PMID 37898636, 2023). "In melanoma, MITF may interact with other genes and proteins involved in the development and progression of this cancer." (PMID 37504268, 2023). "Notch signalling has been described to initiate melanoma progression by inhibiting MITF function." (PMID 36899008, 2023). "Importantly, the enforced inability of (patient-derived) melanoma cells to downregulate MITF diminished their sensitivity to IFNγ." (PMID 36812891, 2023). "Interestingly, in primary melanocytes and UACC62 melanoma cells, MITF expression has been shown to decrease under hypoxia in an HIF-1α-dependent manner." (PMID 36901857, 2023). "Understanding the role of SOX10 and MITF in RTK regulation may disclose how treatment‐induced transcriptional reprogramming could be utilized in the optimization of melanoma treatment strategies." (PMID 36251678, 2023). "Since binding of the K206Q mutant accurately mimicked binding of the acetylated K206 protein in vitro, we next established human 501mel melanoma cells in which HA-tagged WT MITF, as well as the K206Q and K206R mutants, were stably expressed from a doxycycline-inducible promoter." (PMID 37770430, 2023). "To determine whether these results bear clinical relevance, we analyzed MITF expression as well as its target genes in The Cancer Genome Atlas (TCGA) melanoma cohort." (PMID 36812891, 2023). "The effects of TFEB on melanoma metabolism are similar to the effects of MITF." (PMID 37160873, 2023). "The merit of FIR-preconditioning might influence MITF-Akt-mTOR-exosome trajectory both in normal cells and the tumor microenvironment in melanoma." (PMID 37123908, 2023). "The researchers suggested that MITF downregulation might contribute to the resistance of melanoma cells to cytotoxic drugs." (PMID 37504268, 2023). "In the case of MITF, a marker proclaimed as a “phenotype switch” in melanoma, a statistically significant increase in expression was observed in the MNT-1 (p < 0.0001, approximately 3-fold) compared to MelJuSo, while in VMM1 it was significantly down-regulated (p < 0.001)." (PMID 37047539, 2023). "Notably, in circulating tumor cells (CTCs), heterogeneity was confirmed through analysis of MITF expression levels within circulating melanoma cell clusters." (PMID 36675114, 2023). "The microphthalmia transcription factor (MITF) plays a vital role in melanoma cells." (PMID 36989239, 2023). "We next investigated the factors that promote UPP1 expression and growth on uridine by integrating our results with CCLE data to prioritize transcription factors, which highlighted MITF as a strong candidate in melanoma cells, both at the protein and the transcript level." (PMID 37198474, 2023). "Another study that provides insights into the potential impact of MITF mutations on treatment response in the context of BRAF and NRAS mutations found that melanomas with concurrent NRAS and MITF mutations had distinct gene expression patterns and exhibited resistance to MAPK pathway inhibition." (PMID 37504268, 2023).
melanoma (continued). "Some RTK family members like EGFR may be expressed in MITF-low melanoma cells, and under this circumstance, the EGFR expression is linked to a pro-invasive and pro-metastatic melanoma phenotype with resistance to BRAF/MEK inhibitors." (PMID 36747120, 2023). "However, a study on the reprogramming phase in melanoma suggests MITF/SOX10 and AP1/TEAD as being the master regulators of the proliferative and the invasive transcriptome, respectively." (PMID 36251678, 2023). "MITF is the master regulator of cell differentiation in melanocytes and melanoma." (PMID 37898636, 2023). "The purpose of this study was to perform a mutational analysis of the seven candidate melanoma susceptibility genes (ACD, BAP1, MC1R, MITF, POT1, TERF2IP, and TERT) in high-risk melanoma patients (familial melanoma and MPM) from southeastern Brazil, besides the CDKN2A and CDK4 genes." (PMID 37958811, 2023). "Because MITF is essential for melanoma development and GREB1 expression, GREB1 may mediate MITF-dependent melanomagenesis." (PMID 37658191, 2023). "Our data suggest that targeting MITF could be a promising approach in combination with immunotherapy, since its downregulation in melanoma cells under T cell attack contributes to their propensity to be eliminated." (PMID 36812891, 2023). "Hence, these findings suggest that the activation of ERK by A-alum-1 also suppresses α-MSH-induced melanogenesis by interrupting MITF nuclear accumulation in melanoma cells." (PMID 37834109, 2023). "However, further studies have shown that MITF is somatically amplified in ~10% of primary cutaneous melanomas and plays a role in promoting the survival of melanoma cells." (PMID 36901857, 2023). "Furthermore, cAMP-mediated MITF expression transcriptionally activates HIF-1α in B16-F10 melanoma cells." (PMID 36901857, 2023). "Accordingly, siRNA-mediated depletion of MITF decreased UPP1 expression in melanoma cells." (PMID 37198474, 2023). "Therefore, understanding the complex interplay between these signaling pathways and the transcription factor MITF for melanogenesis is essential for developing novel cosmetics and therapeutics for pigmentation disorders and melanoma." (PMID 37834109, 2023). "However, human melanoma tumors are quite heterogeneous, with stem-like cell populations as well as more differentiated populations expressing MITF, TYR, and MELANA." (PMID 37270599, 2023). "It has been reported that MiTF is a factor that supports melanoma stem cells properties." (PMID 37608347, 2023). "Based on the expression levels of MITF, two melanoma cell populations have been identified." (PMID 37370757, 2023). "To further understand the mechanisms underlying MITF downregulation by A-alum-1, we investigated whether the inhibition of MITF nuclear localization by A-alum-1 involves ERK activation in two melanoma cell lines, B16F1 and SK-Mel-28." (PMID 37834109, 2023). "The researchers of this study even proposed that MITF amplification might be a predictive marker for chemotherapy sensitivity in melanoma." (PMID 37504268, 2023). "Furthermore, among the top 25 genes highly correlated with GREB1 gene expression in melanoma, 16 genes were known targets of MITF, such as MLANA and PMEL." (PMID 37658191, 2023). "We have demonstrated that stress-mediated activation of HDAC8 leads to a switch from MITF- to Jun-driven transcriptional programs in melanoma cells that leads to the adoption of a transcriptional state with characteristics of the previously reported NCSC state." (PMID 38030596, 2023).
melanoma (continued). "The melanoma “phenotype‐switch” model describes how cells transition in response to microenvironmental signals and Melanocyte Inducing Transcription Factor (MITF) activity from a proliferative/differentiated to a mesenchymal‐like invasive/dedifferentiated state." (PMID 35156326, 2022). "MITF is recognized as a master regulator of melanocytes required for the development, growth and survival of melanocytes and as a melanoma oncogene amplified in 30–40% of melanomas." (PMID 35563798, 2022). "Moreover, melanoma cell lines switch between an MITF-driven proliferative and a YAP1-driven invasive state which both have been demonstrated experimentally to be associated with respective gene signatures." (PMID 35798875, 2022). "However, mechanisms by which MITF inhibits gene expression in melanoma cells and in-vivo remain to be elucidated." (PMID 35580127, 2022). "In addition, microphthalmia-associated transcription factor (MITF) is involved in the control of proliferation and differentiation of melanocytes, and is also associated with melanoma development and progression." (PMID 35883768, 2022). "Additionally, amplification of the MITF locus and functional upregulation of MITF are potent drivers of melanoma." (PMID 35406743, 2022). "In melanoma, constitutive activation of ERK is associated with a marked degradation of MITF." (PMID 35883768, 2022). "Thereafter, we tested whether MITF mediated the functioning of Wnt/β-catenin signaling in melanoma cell ferroptosis." (PMID 36429010, 2022). "Moreover, melanoma cell lines with MITF promoter hypermethylation were heavily enriched in cases belonging to the MITFlo group as shown in the UMAP analysis." (PMID 36040798, 2022). "It has been shown that increased expression of the MITF oncogene reduces the sensitivity of melanoma cells to targeted therapy by several dozen times compared to cells with wild-type protein, although there are also contradictory results, which are described in the next chapter." (PMID 35565444, 2022). "MITF-low melanomas were described to be more invasive and MITF-high melanomas more proliferative." (PMID 35580987, 2022). "Thus, in aggressive melanoma tumors with acquired resistance, MITF and AXL levels correlate inversely." (PMID 35956175, 2022). "In human melanoma cell lines, the microphthalmia-associated transcription factor (MITF) directly controls PGC-1α expression; hence, the MITF/PGC-1α axis can regulate mitochondrial oxidative phosphorylation and rescue the oxidative stress of reactive oxygen species (ROS)." (PMID 35515121, 2022). "Although MITF clearly anticorrelates with immune infiltration into melanomas, whether MITF plays a role in vivo in regulating immune cell infiltration is not understood." (PMID 35771179, 2022). "In addition, we showed that BPTF transduces certain key pro-proliferative effects mediated by the transcription factor MITF in melanoma." (PMID 36530982, 2022). "This enzyme regulates the MITF–PGC1a transcriptional axis to enhance melanoma growth." (PMID 36224606, 2022). "In this study, we identify a previously unknown redox regulatory mechanism that controls the function of MITF, a transcription factor that plays a critical role in both pigmentation and melanoma." (PMID 36291795, 2022). "In conclusion, MITF’s role in melanoma cells is important and complex." (PMID 35682684, 2022). "In contrast, none of the 7 participants with FH or FLCN mutations were reported to have clinical indicators of HLRCC or BHD syndrome and none of the 10 carriers of P MITF variants had a past history of melanoma." (PMID 35441217, 2022). "Previously, applying both in silico and in vitro experimental models, we demonstrated that interaction between ciprofloxacin and MITF and Mcl-1 could affect viability and apoptosis of melanoma cells." (PMID 36045272, 2022).
melanoma (continued). "In addition, RTK (EGFR), E-cadherin (CDH1), and MITF are also involved in the transformation of normal melanocytes to benign moles, atypical hyperplasia moles, and melanoma." (PMID 35893303, 2022). "Hence, in contrast to the controversial context-dependent regulation of MITF within tumorigenesis and progression of melanoma, our findings show that MITF acts straightforwardly as an oncogene in GC." (PMID 36268034, 2022). "However, given the critical role of MITF in so many aspects of the developmental and therapeutic response to BRAFinh, the possibility of targeting USP13 activity as responsible for MITF stability needs to be further studied in some aspects of melanoma therapy." (PMID 35884430, 2022). "FBXW7 expression was detected downregulated, which is correlated with elevated expression of mitochondrial functional genes as well as poor prognosis of melanoma patients, dependent on its downstream MITF/PGC-1α pathway satisfying the metabolic needs of tumor cells." (PMID 35515121, 2022). "In addition, since BRAF suppresses mitochondrial function via the downregulation of MITF, melanoma cells treated by BRAF-targeted drugs restore oxidative phosphorylation to maintain their survival, leading to adaptive resistance to targeted therapy." (PMID 36003368, 2022). "However, although regulation of RagD has been reported in Hela cells engineered to ectopically overexpress MITF, it has yet to be observed in a physiological setting in melanoma." (PMID 35912100, 2022). "To understand whether MITF promoter–methylated melanoma cells can undergo phenotype switching in NOD/SCID-γ (NSG) mice, we selected 1 cell line that expresses SOX10 (MM383) and 1 that does not express SOX10 (IGR-39)." (PMID 36040798, 2022). "MITF has been shown to promote cell survival in melanoma cells through several mechanisms." (PMID 35682684, 2022). "Together, targeting the Wnt/β-catenin-MITF pathway might be an effective strategy for potentiating ferroptosis and enhancing the effectiveness of anti-PD-1 melanoma immunotherapy." (PMID 36429010, 2022). "MITF-methylated melanomas have diverse functional phenotypes discriminated by SOX10 expression." (PMID 36040798, 2022). "MITF is essential for melanocyte development, it regulates the expression of pigment-producing enzymes and also plays a central role in melanoma: it induces the escape from innate immunity, reprograms focal adhesion and the extracellular matrix, and regulates starvation-induced autophagy." (PMID 35956175, 2022). "It has been reported that hypoxia induces MITF transcriptional repression in melanoma." (PMID 35092699, 2022). "It is interesting to discover that aging fibroblasts related to aged melanoma are more invasive and were shown to secrete frizzled related protein 2 (sFRP2), inhibiting β-catenin and downregulate expression of MITF and apurinic endonuclease (APE1), rendering cells resistant to BRAFi." (PMID 36181568, 2022). "MITF activity strongly influences the phenotype of melanoma cells and determines its invasiveness." (PMID 35719931, 2022). "Furthermore, the transcriptomic classification of melanoma includes the immune, keratin, and MITF-low subtypes." (PMID 36303162, 2022). "SMARCD1 and SMARCD2 both interact with MITF and may have important roles in melanocyte development and melanoma." (PMID 35323214, 2022). "However, ERK overactivation only correlated with reduced MITF levels and cell growth defects in melanoma cells with high basal levels of MITF." (PMID 35580987, 2022). "In addition, a major reason for growth arrest in some melanoma cell lines is the downregulation of MITF, a lineage-specific transcription factor critical for melanocyte and melanoma cell proliferation." (PMID 35197475, 2022).
melanoma (continued). "To corroborate this finding, we evaluated the mRNA expression level of the microphthalmia-associated transcription factor (MITF) and the tyrosinase enzyme (TYR), the two most important genes involved in melanin synthesis and in melanoma development, with a qPCR analysis." (PMID 36670903, 2022). "MITF regulates CDK2 in melanoma, which is critical for tumor cell growth." (PMID 36551682, 2022). "In addition, the key lipogenic enzyme SCD1 is also the target of MITF that mediates the process of fatty acid composition and melanoma phenotype switching." (PMID 36429010, 2022). "In the MITF-rheostat model, melanoma cells are organized horizontally." (PMID 35631574, 2022). "Accordingly, bulk and single-cell RNA sequencing of melanoma biopsies differentiated cells into two phenotypic states corresponding to two mutually exclusive gene expression signatures driven by the transcription factors MITF and AP-1/TEAD." (PMID 36497341, 2022). "In vivo and ex vivo characterization of MITF-methylated melanoma cells." (PMID 36040798, 2022). "Melanomas display immunostaining characteristics of melanocytic differentiation such as protein melan-A (MelanA) or MART1, microphtalmia-associated transcription factor (MITF), Human Melanoma Black (HMB45), SRY-related HMG-box 10 protein (SOX10), and S-100 protein positivity." (PMID 35334544, 2022). "This correlation from a large human melanoma dataset supports our hypothesis that MITF and DUSP4 are functionally co-dependent." (PMID 35580987, 2022). "We then restored MITF activity by lowering the water temperature and followed melanoma recurrence." (PMID 35929478, 2022). "Melanocyte and melanoma differentiation is critically dependent on MITF." (PMID 35323214, 2022). "MITF could potentially be an attractive target for melanoma therapy but the drug-targeting of MITF is highly challenging." (PMID 35158973, 2022). "Thus, we performed bisulfite Sanger sequencing of the MITF promoter to investigate the methylation pattern in 51 out of the 86 melanoma cell lines analyzed by RNA-Seq." (PMID 36040798, 2022). "In melanoma development and progression, the role of MITF is rather ambiguous." (PMID 35580987, 2022). "SEMA6A has been shown to be deregulated together with many other cancer-related genes in the complex mechanism driven by BRAFV600E on melanoma tumorigenesis; Guo and collegues also indicated the transcription factor MITF as a main mediator of BRAFV600E-driven transcription reprogramming." (PMID 35440004, 2022). "What is more important is that pharmacological inhibition of either β-catenin or MITF could increase the treatment effect of anti-PD-1 antibodies in a preclinical mouse model by facilitating melanoma cell ferroptosis." (PMID 36429010, 2022). "Furthermore, the MITF and tyrosinase enzyme are responsible for pigmentation in both nevi and melanoma cells with a proliferative phenotype." (PMID 35956175, 2022). "The MITF-low (MITFlo) melanoma subtype is often enriched in tumors resistant to targeted therapy." (PMID 36040798, 2022). "This seemingly contradictory conclusion happened simultaneously in MITF characterized as both a melanoma oncogene and an invasion suppressor, which may be a kind of “Rheostat model”." (PMID 35433681, 2022). "MITF interconnects with EMT to control the phenotypic plasticity in melanoma cells." (PMID 35406721, 2022). "Another commonly used marker for melanomas, MITF, could have provided valuable information in this case." (PMID 35198980, 2022). "The intervention of Wnt/β-catenin and MITF might be explored as a melanocytic-specific strategy to enhance the effectiveness of immunotherapy in melanoma." (PMID 36429010, 2022). "Melanoma cells can interconvert between two main states: the proliferative/differentiated MITFhigh phenotype, also referred to as the “melanocyte-like” state, and the invasive/undifferentiated MITF-low phenotype, referred to as the “mesenchymal-like” state." (PMID 35406721, 2022).